IL13 (interleukin 13)
Diseases named in the same sentence as IL13 in open-access papers (continued):
Sharing a sentence is not in itself a finding about the gene and the disease.
asthma (continued). "In addition, asthma therapy with new biologicals, for example anti–IL-5 or anti–IL-13, appears to be far more effective if patients are selected using cellular (eg, eosinophils) or molecular (eg, periostin) biomarkers." (PMID 26334389, 2016). "Therefore, IL-13 has been widely recognized as playing an important role in the pathophysiology of asthma." (PMID 26975422, 2016). "In our study, IL-13 production was greater in asthma cells compared to controls." (PMID 27716212, 2016). "Investigators from Shanghai set out to determine if IL-13+ ILC2s correlated with asthma severity." (PMID 27610226, 2016). "As part of the Th2 hypothesis of asthma, IL-13 has been shown to play a critical role in various aspects of airway inflammation and epithelial remodeling including goblet cell metaplasia and epithelial-mesenchymal signaling." (PMID 26334389, 2016). "In addition, IL-13, activating B cells, is a key mediator of allergic disease and asthma and, in fact, it is strongly increased in these abnormal immune responses." (PMID 27509021, 2016). "This is relevant since local IL-13 release can induce all of the features of AAD/asthma." (PMID 27309732, 2016). "In addition, genes discovered in genome-wide association studies of asthma (RORα, IL-13, IL-33, IL-1RL1; which are all related to ILC2) suggest a key role for ILC2 in asthma." (PMID 26727464, 2016). "In mice, it could be shown that the expression of TSLP, IL4, IL5 and IL13 induces atopic dermatitis as well as asthma, and IL5 knockout mice exposed to allergens are less prone than wild-type to develop skin eosinophilia and epidermal thickening." (PMID 27431613, 2016). "Furthermore, IL-13-induced periostin can be measured in peripheral blood and is used as a companion marker for predicting the efficacy of anti-IL-13 antibodies in human asthma patients." (PMID 26975422, 2016). "Several mediators/modulators are involved in asthma pathogenesis and in hyperresponsiveness such as Th2 cytokines (IL-5, IL-4, and IL-13), IL-17, leukotrienes, nitric oxide, Rho kinase, cholinergic system, and others that were clearly evaluated in humans and animal models." (PMID 27445433, 2016). "Furthermore, intranasal delivery of let-7 mimic resulted in a decrease in IL-13 levels and alleviated asthma features." (PMID 27187364, 2016). "In addition, the relative contribution of IL-5 and IL-13 production by ILC2s in human asthma in comparison to Th2 cells, other innate cells and structural cells, like epithelial cells, needs to be further elucidated." (PMID 26965110, 2016). "IL-31 is a Th2 cytokine, to determine whether its serum concentration is correlated with other asthma related Th2 cytokines in asthma, we further measured the Th2 related cytokines IL-5, IL-13 and thymic stromal lymphopoietin (TSLP)." (PMID 26956917, 2016). "Furthermore, anti-interleukin-13 therapy improves the lung function of patients with severe asthma who had a pretreatment profile consistent with interleukin-13 activity." (PMID 27547445, 2016). "DPP4 is a one the gene that variable in untreated asthma and IL-13 stimulation." (PMID 26975422, 2016). "In support of these previous findings, a recent report using a genome-wide approach identified an IL13-induced DNA methylation signature in adult asthmatic airways, which contains two co-methylation modules related to asthma severity and eosinophilia respectively." (PMID 27777592, 2016). "IL-13 has been shown to induce mucus hypersecretion and AHR in murine asthma models in which cysteinyl-LTs might be causative agents of AHR." (PMID 27267050, 2016). "Both have been demonstrated to improve lung function and possibly reduce asthma exacerbations, but only in patients with severe asthma with biomarker evidence of a type-2 phenotype, demonstrated by elevated serum periostin levels or elevated IL-13 levels in sputum." (PMID 27942351, 2016). "We demonstrated that DPP4 is expressed in BECs in human asthma and is induced by IL-13." (PMID 26975422, 2016).
asthma (continued). "Based on previous findings, we hypothesized that IL-25 in asthma could promote the activation of nuocytes, and then in turn induce a large amount of IL-5 and IL-13 to enhance Th2 cytokine responses." (PMID 27617447, 2016). "Asthma is characterized by chronic inflammation of the airways and lungs with marked Th2 response, as showed by high concentrations of interleukin (IL)-4, IL-5 and IL-13, IgE production, mucus and eosinophils influx to airways." (PMID 27454771, 2016). "Moreover, alternatively activated macrophages responded to IL-4 and IL-13, key cytokines in asthma pathology and furthermore, promoted a TH2 environment and airway remodeling." (PMID 27007158, 2016). "Biologicals targeting the Th2-eosinophil nexus such as anti–interleukin (IL)-4, anti–IL-5, and anti–IL-13 are ineffective in asthma as a whole but are more effective if patients are selected using cellular (eg, eosinophils) or molecular (eg, periostin) biomarkers." (PMID 26334389, 2016). "It has been reported that the production and high activity of eosinophils, the hallmark of asthma, was not affected despite inhibition of IL-13." (PMID 27255587, 2016). "However, IL-9 also contributes to pathology in inflammatory bowel disease and autoimmune diseases, in addition to asthma models, where it was shown to induce mucus production, goblet cell metaplasia, expression of IL-13 and airway hypersensitivity." (PMID 26936133, 2016). "Additionally, not only the infiltration of neutrophils and eosinophils but also the levels of IL‐4, IL‐5, and IL‐13 were reduced upon bvPLA2 treatment in OVA‐induced asthma mice." (PMID 26734460, 2015). "The elevated IL-4 and IL-13 levels seen in the present study reinforces the idea that Th2 lymphocytes are key cellular players in directing the early immune response to allergen re-exposure in the sheep asthma model." (PMID 26362930, 2015). "Therefore, biologic targeted therapies have been developed to target the specific molecular pathways to treat asthma, especially those targets at IL-4, IL-5, IL-13, and IgE." (PMID 26064160, 2015). "Further, enhanced levels of IL-13 producing macrophages have been found in the BAL from subjects with severe asthma, suggesting that M2 macrophages may contribute to reduced lung function in asthma patients." (PMID 26362930, 2015). "We hypothesized that airway exposure to HDM allergen would induce or elevate the expression profile of IL-4 and IL-13 during the allergic airway response in this large animal model of asthma." (PMID 26362930, 2015). "Irrespective of the exposure or disease status, methylation of several asthma and allergy-related genes changed over time (IL-4, IL-13, ORMDL3, RAD50), indicating their involvement in developmental processes, while Treg-related genes (FOXP3, RUNX3) remained unchanged." (PMID 26052354, 2015). "IL13 plays a major role in promoting fibrosis in asthma and schistosomiasis." (PMID 26540410, 2015). "After 6 mounts therapy with combination of ICS/LABA in patients with uncontrolled severe persistent asthma we found decreases of serum IL-13, but added the Montelukast in this combination proved superior effect and allow achievement of total control of asthma with subjective clinical improvement." (PMID 27275233, 2015). "Additionally, IL-4 and IL-13 act on bronchial epithelial, endothelial and airway smooth muscle cells, collectively leading to many of the pathophysiological features of asthma." (PMID 26362930, 2015). "Th2-related cytokines (IL-5, IL-6, and IL-13) can contribute to the induction of asthma." (PMID 25658604, 2015). "One study in Chinese children with asthma, has demonstrated that there were significant interactions between IL13 and IL4RA for asthma and between IL13 and the thymus and activation-regulated chemokine (TARC) gene for increased plasma total IgE concentrations in this cohort." (PMID 26196693, 2015). "Interleukin 13 (IL-13) is one of many cytokines responsible for the chronic inflammation of asthma." (PMID 27275233, 2015).
asthma (continued). "IL-13 is one of many cytokines responsible for the chronic inflammation of asthma." (PMID 27275233, 2015). "Importantly, we show that β-CAT-Tg iNKT cells acquired the ability to produce enhanced levels of IL-4 and IL-13 during development that augmented lung inflammation in a mouse model for asthma." (PMID 26482437, 2015). "Rho kinase may also be involved in eotaxin and cytokine (IL-5, IL-13) production and in secretion of matrix metalloproteinase – 9 (MMP-9), tightly associated with fibrosis in asthma and chronic obstructive pulmonary disease (COPD)." (PMID 26646719, 2015). "In the current analysis, higher IL‐10 or IFN‐γ was only associated with asthma in the context of high IL‐5 and IL‐13 productions; children who produced IL‐10 but no IL‐5 (Class 1), or IFN‐γ but no IL‐5 (Class 2) were not at increased risk of asthma." (PMID 26061524, 2015). "DA could dose-dependently inhibited ovalbumin-induced increases in total and eosinophil counts, IL-4, IL-5, and IL-13 levels in lavage fluid in a mouse asthma model." (PMID 26223251, 2015). "In the same context, we applied our M(IL-4, IL-13) signature to predict outcomes in asthma cohorts." (PMID 26302899, 2015). "Moreover, the allergic airway disease model has been in use for over 20 years and predicted the successful outcomes of asthma clinical trials involving anti-IL-13 and anti-IL-4Rα antibodies." (PMID 26605551, 2015). "In asthma, there is ample evidence for goblet cell metaplasia involving the conducting airways; IL-4 and IL-13 also induce the production of TGF-β by epithelial cells that, through autocrine signaling, results in the mucus metaplasia that is characteristic of Th2-mediated inflammation." (PMID 26048391, 2015). "IL-5 and IL-13 are classical Th2 cytokines, promoting B cell growth and maturation, activating eosinophil granulocytes, promoting the defense against parasites, in addition to playing active roles in asthma and allergy disorders." (PMID 24714360, 2014). "Additionally, levels of IL-13, a well-known regulator of mucous cell metaplasia and inflammation in Th2-mediated asthma, were measured in whole lung tissue and BALF for mRNA and protein expression, respectively." (PMID 24499286, 2014). "Other factors such as the cytokine interleukin 13 (IL-13) have been shown to affect goblet cell differentiation in the airways, with goblet cell hyperplasia reported to be a major contributing factor in diseases like asthma." (PMID 24533135, 2014). "We hypothesized that GGsTop could attenuate asthma in the IL-13-driven model of allergic airway inflammation in mice and represent a valuable alternative to acivicin as a clinical therapeutic." (PMID 25132819, 2014). "IL-13 induced goblet cell hyperplasia is one of the major hallmarks of the respiratory epithelium in asthma and our finding, that p63 knockdown cells are unable to respond to IL-13, suggests a role for this transcription factor in upper airway basal cell differentiation." (PMID 24533135, 2014). "For example, IL-13 has been demonstrated to induce goblet cell hyperplasia in human airway epithelial cells in vitro, and blocking IL-13 significantly inhibits mucus overproduction in a murine model of asthma." (PMID 24892823, 2014). "HDM-specific IL-13 responses at the age of 3 years, but not at 5 and 8 years, were significantly associated with asthma at 8 years." (PMID 24875149, 2014). "Asthma is one of the airway hyperresponsive diseases which can be characterized by the accumulation of inflammatory cells, increase in mucus production, release of certain Th2 cytokines, IL-4, IL-5, and IL-13, and increased levels of IgE." (PMID 24936861, 2014). "The pathogenesis of asthma has been related to an imbalance of cytokines released from T helper (Th) cells, with an increase in Th2 type cytokines (Interleukin (IL) IL-4, IL-5, and IL-13) and a decrease in Th1 cytokines (IFN-γ and IL-2)." (PMID 24450480, 2014).
asthma (continued). "IL-13 is another Th2 cytokine thought to be a central mediator of inflammation in asthma." (PMID 23555579, 2013). "Michel and colleagues examined the effect of farm exposure on DNA-M of ten asthma candidate genes and found that DNA-M at one IL13 site (spanning rs1800925; similar to the site in our study) was more methylated in the exposed group compared to the non-exposed group." (PMID 24314122, 2013). "Pinelliae rhizome and Citrus reticulata and their combinational prescription have deep inhibitory effects on airway inflammation in a murine model of asthma and it was mediated by suppression of Th2 cytokines (IL-4, IL-5, IL-13), IgE, eosinophil CCR3 expression in lung." (PMID 24367979, 2013). "Furthermore, in human subjects with asthma, the IL-13 concentration in peripheral blood was increased across disease severity in a stable state and was up-regulated at exacerbations." (PMID 23437086, 2013). "Severe asthma is also associated with increased IL-17A production and studies in experimental models suggest a critical role for complement-mediated regulation of the IL-23-TH17 axis by enhancing IL-13-driven responses." (PMID 24223970, 2013). "As a result, STAT6 gene expression is increased and asthma is induced via an IL-4/IL-13 pathway." (PMID 23861779, 2013). "However, few studies have explored the interactive effects between IL-13 haplotypes and environmental exposures on childhood asthma." (PMID 23382814, 2013). "Joint effects of carpet use and IL-13 haplotype h1011 on asthma phenotypes among children." (PMID 23382814, 2013). "For example, IL-13 plays an important role in regulating the airway inflammation in asthma." (PMID 24032029, 2013). "Significantly different allelic distributions between the affected and unaffected groups were found for: the IL13 promoter SNP (rs1800925) in asthma (P = 0.038); the IL13exonic SNP (rs20541) in asthma (P = 0.0007) *; the ERBB1 SNP (rs2227983) in bronchitis (P = 0.007)." (PMID 23551418, 2013). "Furthermore, IL-13 exhibits stimulatory activity to multiple cell types that are involved in asthma, including B cells, mast cells, eosinophils, pulmonary epithelial cells, fibroblasts and airway smooth muscle cells." (PMID 23865080, 2013). "Interleukin-13 (IL-13) is involved in the pathogenesis of asthma." (PMID 24314122, 2013). "Household carpet use appears to modify the effects of IL-13 gene on wheeze and late-onset asthma." (PMID 23382814, 2013). "Interestingly, previous studies with peripheral blood mononuclear cells also suggested CCL26 as a potential IL-13-related biomarker in the context of asthma and our findings, in unmanipulated donor nasal epithelial cells, support this." (PMID 23402658, 2013). "IL-13 was one of the most studied of the candidate genes for asthma." (PMID 23437086, 2013). "Individuals with mutant T-allele at position −1111C>T of the human IL-13 gene promoter have a 1.81 times likelihood to develop asthma compared to those without this allele at this SNP." (PMID 23865080, 2013). "Joint effects of carpet use and IL-13 genotypes on asthma phenotypes among children." (PMID 23382814, 2013). "In the subgroup analysis by atopic status, the IL-13 −1112C/T polymorphism was significantly associated with risk of atopic asthma (OR = 1.25, 95% CI 1.07–1.45, P = 0.004) but not with non-atopic asthma risk (OR = 1.28, 95% CI 0.97–1.68, P = 0.08)." (PMID 23437086, 2013). "Furthermore, IL-13 expression was related to asthma control and the intensity of eosinophilic inflammation." (PMID 23841068, 2013). "Strong experimental evidence demonstrated that IL-13 could direct many of the important features of airway inflammation and remodeling in asthma." (PMID 23841068, 2013). "IL-13 was primarily produced by Th2 CD4+ T cells after allergen irritation, and it may induce the entire pathogenic pathway of asthma independently of traditional cells, such as mast cells and eosinophils." (PMID 23382814, 2013).
asthma (continued). "Moreover, in the first large pharmacogenetic, placebo-controlled investigation of the IL-4/IL-13 pathway, three doses (1 mg, 3 mg, or 10 mg twice daily for 12 weeks) of inhaled pitrakinra were tested in patients with moderate-to-severe asthma." (PMID 23853765, 2013). "IL-13 is thought to the pathogenesis of allergen-induced asthma." (PMID 23663500, 2013). "Collectively, these results indicated that IL-13 might have an important role in the pathophysiology of asthma." (PMID 23841068, 2013). "The elevated level of IL-10 in the serum of asthma subjects indicated an increase in Type-2 activity through which the production of IL-4 and IL-13 may promote an isotype switch to IgE." (PMID 23226977, 2012). "Recent experimental evidence indicates that chlamydial lung infection may induce or worsen several hallmarks of asthma including airway inflammation, airway hyperresponsiveness, mucous hypersecretion and IL-13 production." (PMID 22545149, 2012). "Therapeutical interventions in allergic diseases such as allergen-induced asthma specifically targeting IL-4, IL-5 or IL-13 cytokines caused none to moderate improvement regarding disease severity and symptoms." (PMID 22853438, 2012). "Several reports have demonstrated that TH2-type cytokines, including IL-4 and IL-13, enhance IL-17–induced release of IL-6 from fibroblasts, suggesting that IL-17 might be involved in asthma, which is a TH2-mediated disease." (PMID 22203879, 2012). "Therefore, Th2 cells are important primarily in the airways, and Th2 cytokines such as interleukin (IL)-4, IL-5, and IL-13 play pivotal roles in the pathophysiology of asthma." (PMID 23244755, 2012). "Although IL-5 and IL-13 are known to be involved in the pathogenesis of asthma, no breast milk study has demonstrated associations with AS previously." (PMID 22805009, 2012). "Indeed, out of around 3000 peer-reviewed publications implicating IL-13 as a central mediator in asthma, only four relate to direct evidence in human asthma." (PMID 23189057, 2012). "Some genes, such as those coding IL-13 and IL-17F, might be involved in a global model of shared genetic factors for atopy, asthma and COPD." (PMID 22537093, 2012). "Home dampness combined with each one of the genes STAT6, IL13 and ADRB2 could raise the asthma risk." (PMID 22355322, 2012). "Homozygous carriers of HLX1 SNP rs3806325, which was previously associated with an enhanced risk for asthma, especially non-atopic asthma in childhood, showed increased levels of IL-13 (TH2) and additionally enhanced IL-6 secretion in this cord blood study." (PMID 22303482, 2012). "Thus, IL-13 and IL-5 cytokines are considered to play a prominent role in the pathophysiology of asthma." (PMID 22805009, 2012). "In asthma, IL-13 is a key molecule that links CLCA1 expression with mucus production." (PMID 22731784, 2012). "Our results suggest that during IL-13-mediated stimulation, simvastatin may suppress airway epithelial pro-inflammatory responses relevant to asthma pathogenesis." (PMID 22583375, 2012). "Home dampness combined with each one of the genes STAT6, IL13 and ADRB2 could also raise the asthma risk." (PMID 22355322, 2012). "Using an allergic mouse model of asthma, we previously demonstrated a benefit of statins in reducing peribronchiolar eosinophilic inflammation, airway hyperreactivity, goblet cell hyperplasia, and lung IL-4 and IL-13 production." (PMID 22583375, 2012). "Although IL-13 and IL-4 are both central Th2 cytokines in the immune system and potent activators of inflammatory responses and fibrosis during Th2 inflammation, recent studies demonstrated that these cytokines exerted a distinct role in asthma pathology." (PMID 22414623, 2012). "It involve in both the innate and adaptive immune responses and may be one of the major sources of IL-13 in asthma in mouse models." (PMID 23094102, 2012).